NLRP3 (NLR family pyrin domain containing 3)
Diseases named in the same sentence as NLRP3 in open-access papers (continued):
Sharing a sentence is not in itself a finding about the gene and the disease.
lymphoma (continued). "Nevertheless, we will focus on the less studied NLRP3 inflammasome implication in the process of lymphopoiesis, considering lymphomas, especially B-cell NHLs, as classified based on the normal counterpart, or cell of origin, from which they arise." (PMID 38397043, 2024). "NF-κΒ, a known contributor to the pathogenesis of various lymphoma subtypes, is also a factor inducing NLRP3 inflammasome priming." (PMID 38397043, 2024). "Considering that lymphomas comprise a heterogeneous group of hematologic neoplasms, both tumor-promoting and tumor-suppressing properties were attributed to the NLRP3 inflammasome, affecting neoplastic cells and immune cells in the tumor microenvironment." (PMID 38397043, 2024). "This can be one of the main reasons NLRP3 inflammasome is found to be dysregulated during lymphoma development and progression." (PMID 38397043, 2024). "Apart from its effect on BCR signaling and its ability to induce apoptosis in lymphoma cells, Luxeptinib was also shown to inhibit NLRP3-mediated IL-1β secretion in monocytic cell lines." (PMID 38397043, 2024). "Given the heterogeneity of the multiple lymphoma subtypes, in this review, we try to underscore the role of the NLRP3 inflammasome in lymphomagenesis." (PMID 38397043, 2024). "An overactivated P2X7R-NLRP3 inflammasome axis was reported in SS patients who develop lymphoma, while persistent NLRP3 inflammasome activation in monocytes and macrophages driven by cf-DNA and nucleosomes arising from epithelial SG cells was also described." (PMID 38397043, 2024). "Research highlighted that certain polymorphisms in the genes encoding for NLRP3 inflammasome-related molecules are associated with increased susceptibility to B-cell NHL development and correlate with lymphoma patients’ survival and prognosis." (PMID 38397043, 2024). "In lymphoma, the NLRP3 inflammasome was found to upregulate PD-L1 expression, resulting in T cell exhaustion." (PMID 39796680, 2024). "The NLRP3 inflammasome upregulates PD-L1 expression and participates in immunosuppression of lymphoma." (PMID 36541912, 2022). "The NLRP3 inflammasome has been shown to regulate immunosuppressive response by increasing PD-L1 expression in the lymphoma cells." (PMID 35897704, 2022). "Essentially, mRNA levels of NLRP3, IL-1β, IL-18, caspase-1, and P2 × 7R, components of the NLRP3 inflammasome, were significantly elevated in SjS patients who subsequently developed lymphoma." (PMID 35897704, 2022). "Administration of MCC950, small-molecule NLRP3 inhibitor, repressed lymphoma expansion and downregulated PD-L1." (PMID 35897704, 2022). "The activated NLRP3 pathway contributed to the lymphoma’s growth and inhibited apoptosis in a diffuse large B-cell lymphoma (DLBCL) cell line culture." (PMID 35897704, 2022). "NLRP3 inflammasome can induce the anti-dexamethasone effect of lymphoma cells through IL-18, thereby inhibiting apoptosis and promoting tumor proliferation." (PMID 34805183, 2021). "In lymphoma, NLRP3 inflammasome blockade in vivo suppressed tumor growth and ameliorated antitumor immunity by decreasing MDSCs, TAMs, and Tregs through the effector cytokine IL-18." (PMID 35003065, 2021). "For instance, in malignant lymphoma, NLRP3-inflammasome activation correlated with up-regulation of PD-L1, which contrasts with the discordant pattern in our MDS patients and is more reminiscent of an inflammatory condition." (PMID 34830867, 2021). "Another study from the same group has shown that NLRP3 inflammasome activation promoted lymphoma cells proliferation and inhibited apoptosis through up-regulation of c-myc and bcl-2 anti-apoptotic factors." (PMID 31379813, 2019).
lymphoma (continued). "As for another NLRP3 effector molecule, though plasma IL-1β level in newly-diagnosed lymphoma patients was significantly higher than in controls (p = 0.0031), no significant decrease was found after chemotherapy remission (p = 0.1015)." (PMID 29312552, 2017). "Interestingly, TRIM65 was shown to downregulate NLRP3 inflammasome activation, while in the setting of lymphoma, TRIM65 overexpression favors lymphoma cell survival via the ERK1/2 signaling pathway." (PMID 38397043, 2024). "However, in vivo blockade of the NLRP3 inflammasome inhibits lymphoma growth and suppresses anti-tumor immunity." (PMID 38177104, 2024). "Finally, we review current evidence supporting NLRP3 inflammasome targeting as a potential therapeutic strategy for lymphomas." (PMID 38397043, 2024). "Besides the extensively studied role of the NLRP3 inflammasome in innate immunity, increasing evidence highlights its implication in various malignancies, amongst them lymphomas." (PMID 38397043, 2024). "Therefore, in this section, we first briefly analyze the regulation of the NLRP3 inflammasome components and related pathways by TRIMs, and we continue by reviewing research results implicating TRIMs in lymphoma development." (PMID 38397043, 2024). "Considering that either NLRP3 or IL-18 inhibition in lymphoma mouse models leads to a decrease in PD-1/TIM-3-expressing T-cells, MDSCs, tumor-associated macrophages, and regulatory T-cells, it can be proposed that IL-18 mediates the accumulation of immunosuppressive cell populations." (PMID 38397043, 2024). "Further research is imperative to define the regulators of NLRP3 inflammasome activation in lymphoma, while preliminary data support that its targeting could provide additional treatment modalities to cover unmet therapeutic needs." (PMID 38397043, 2024). "NLRP3 inflammasome activation in lymphoma cells tends to generate an immune-suppressive TME." (PMID 38397043, 2024). "Therefore, in this review, we will try to unravel the less explored involvement of the NLRP3 inflammasome in the development of lymphomas." (PMID 38397043, 2024). "Further understanding of the mechanisms regulating NLRP3 inflammasome activation during lymphoma development and progression can contribute to the investigation of novel treatment approaches to cover unmet needs in lymphoma therapeutics." (PMID 38397043, 2024). "However, the combination of NLRP3 blockers with anti-PD-L1 treatment showed antagonistic effects in lymphoma." (PMID 35739593, 2022). "Thus, NLRP3 blockers combined with anti-PD-L1 treatment exerted antagonistic effects during lymphoma therapy." (PMID 35003065, 2021). "In order to further explore the role of NLRP3 inflammasome in B-cell lymphoma progression, they employed a murine lymphoma model by injecting subcutaneously A20 cancer cells into 4-week-old female BALB/C mice and treating them with the NLRP3-inhibitor MCC950 or with placebo." (PMID 34441758, 2021). "The recent observation that high glucose is able to activate the EBV lytic switch via the NLRP3 inflammasome and that increased lytic activation predisposes the development of EBV-lymphomas together provide a mechanistic basis for this important clinical observation." (PMID 34066537, 2021).
lymphoma (continued). "A previous study demonstrated that activated NLRP3 increases IL-18 in patients with lymphoma." (PMID 33096896, 2020). "In addition, NLRP3 inflammasome increases IL-18 and IL-1β production, thereby promoting tumor cell proliferation and inhibiting apoptosis during lymphoma development." (PMID 32063899, 2019). "NLRP3 inflammasome could be activated by ATP plus LPS in lymphoma cells accompanied with the increasing expression of NLRP3-related genes." (PMID 29312552, 2017). "Inflammasomes play important roles in the pathogenesis of tumors, but the roles of NLRP3 inflammasome in the lymphoma remain unclear." (PMID 29312552, 2017). "Our study found that the expression levels of NLRP3-related genes IL-18, IL-1β, NLRP3 and caspase-1, were increased after addition of ATP plus LPS, suggesting NLRP3 could be primed and activated in lymphoma cells." (PMID 29312552, 2017). "We have demonstrated the elevated IL-18 in lymphoma patients was decreased after remission and activated NLRP3 inflammasome could induce higher IL-18." (PMID 29312552, 2017). "The activation of NLRP3 may increase the expression of NLRP3-related genes such as IL-18, IL-1β, NLRP3 and caspase-1 in lymphoma cells, thereby promoting proliferation, inhibiting apoptosis, and reducing the anti-tumor effect of dexamethasone." (PMID 29312552, 2017). "Moreover, the role of mtROS in NLRP3 inflammasome priming and the metabolic aberrations described in various lymphomas might be additional contributors to the NLPR3 inflammasome dysregulation." (PMID 38397043, 2024). "For most lymphomas, specifically DLBCL, MALT lymphoma, MCL, PEL, and ΝΚ/Τ-cell lymphoma, NLRP3 inflammasome activation seems to exert a pro-tumorigenic effect." (PMID 38397043, 2024). "We should also consider the differences in the TME of each lymphoma subtype, given the effect of the TME on NLRP3 inflammasome activation and vice versa." (PMID 38397043, 2024). "Remarkably, in vivo administration of the NLRP3 inhibitor, MCC950, repressed lymphoma expansion and reduced the concentrations of IL-1β and IL-18, consequently downregulating PD-L1." (PMID 35897704, 2022). "Significantly, they found that the NLRP3 blockade resulted in delayed tumor progression, and so, to further determine whether this attenuation in tumor growth derived from the reversal of immunosuppression, they analyzed the frequencies of immune cell populations in lymphoma-bearing mice." (PMID 34441758, 2021). "As opposed to B-cell NHLs, there are fewer studies investigating the role of the NLRP3 inflammasome in the pathogenesis of T and NK-cell lymphomas, which is not unexpected given the lower frequency of these lymphoma subtypes." (PMID 38397043, 2024). "As opposed to lymphomas of B-cell origin, in the case of T-cell lymphomas, enhancing the activation of the NLRP3 inflammasome is what exerts antitumor effects." (PMID 38397043, 2024). "Surprisingly, for SS-related lymphomas, research focused on stimulators of NLRP3 activation other than BAFF, acting on non-neoplastic immune cells of the TME." (PMID 38397043, 2024). "As opposed to B-cell lymphomas, where overall NLRP3 inflammasome activation seems to support lymphomagenesis for the majority of the studied lymphoma subtypes, studies for T-cell lymphomas reached diverse conclusions." (PMID 38397043, 2024). "Furthermore, in order to examine the influence of NLRP3 inflammasome on the efficacy of ICB, they used three groups of lymphoma-bearing mice: the first was treated with the MCC950 inhibitor, the second with the anti-PDL1 antibody, and the latter with combination therapy." (PMID 34441758, 2021). "However, the role of NLRP3 inflammasome in the development and therapy of lymphoma has not been reported." (PMID 29312552, 2017). "However, the role of NLRP3 inflammasome in the development and treatment of lymphoma has not been reported until now." (PMID 29312552, 2017).
lymphoma (continued). "The researchers reported significantly higher mRNA expression for P2X7R, NLRP3, caspase-1, IL-18, and IL-1β in patients with SS who developed MALT-NHL over the follow-up, compared to both SS patients who did not develop lymphoma and controls." (PMID 38397043, 2024). "Conversely, despite the suggested involvement in lymphoma development and the progression of TRIM11, TRIM13, TRIM19, TRIM32, TRIM35, TRIM65, data on their possible function regarding NLRP3 inflammasome regulation are lacking." (PMID 38397043, 2024).
non-small cell lung carcinoma (34 papers, 2019 to 2025). A group of at least three distinct histological types of lung cancer, including non-small cell squamous cell carcinoma, adenocarcinoma, and large cell carcinoma. "Another study found that a specific agonist, polyphyllin VI (PPVI), activates the ROS/NF-κB/NLRP3/GSDMD signaling pathway to inhibit non-small cell lung cancer (NSCLC)." (PMID 38553639, 2024). "NLRP3 expression is downregulated in non-small-cell lung cancers, with its expression positively correlating with overall survival." (PMID 39769450, 2024). "The NLRP3 inflammasome was found to be activated in non-small-cell lung cancer, promoting the release of IL-1β and IL-18." (PMID 39201564, 2024). "NLRP3 inhibition has also been shown to prevent the growth and migration of non-small-cell lung cancer cells, indicating a broader role in promoting cancer progression." (PMID 39769450, 2024). "NLRP3 vesicle-mediated inflammatory responses and are related to non-small cell lung cancer progression, which corroborates the OS analysis results of this study." (PMID 38166691, 2024). "For example, the anticancer effects of plant products reniformin A, saikosponin-D, and EEBR are exerted by inducing NLRP3-mediated pyroptosis in non-small-cell lung cancer cells." (PMID 39769450, 2024). "In conclusion, this study investigated the effects of Sophora exigua extract and its active compounds on the NLRP3 inflammasome pathway in non-small cell lung cancer (NSCLC)." (PMID 38026959, 2023). "We were intrigued by genome-wide studies reporting that NLRP3 is frequently altered in non-small cell lung cancer (NSCLC) and BC." (PMID 36746533, 2023). "In the context of non-small cell lung cancer, the activation of the NLRP3 inflammasome pathway in response to LPS and ATP enhanced the cell proliferation and invasive capability of A549 cells." (PMID 38026959, 2023). "Polyphyllin VI induced caspase-1-mediated pyroptosis via the induction of the ROS/NF-κB/NLRP3/GSDMD signal axis in non-small-cell lung cancer." (PMID 34764819, 2021). "Huaier extract exhibits an antitumor effect through promoting NLRP3-dependent pyroptotic cell death in non-small cell lung cancer (NSCLC) cells and NSCLC patients." (PMID 32093389, 2020). "Activation of the NLRP3 inflammasome antagonized the suppressive effect of polydatin on the proliferation and migration of non-small cell lung cancer (NSCLC) cells." (PMID 31492049, 2019). "Finally, the 5-HTR3A receptor has also been reported to facilitate the development and progression of both colorectal and non-small-cell lung cancer through NLRP3 and Wnt3A/β-catenin signaling, respectively, thus confirming its role in carcinogenesis." (PMID 39766077, 2024). "Current reports revealed that activation of NLRP3 in non-small-cell lung cancer could enhance tumor cell proliferation and migration, and NLRP3 expression inhibition could alleviate proliferation and metastasis." (PMID 34239588, 2021). "Thus far, studies on the anticancer activity of polydatin have shown the following: NF-κB suppressed by polydatin, inhibited NLRP3 inflammasome activation and it lead to prevent proliferation and metastasis of non-small cell lung cancer cells." (PMID 34577602, 2021). "This study explored the anti-inflammatory and anti-metastatic properties of morin in non-small-cell lung cancer (NSCLC) cells, focusing on its effects on the NLRP3 inflammasome and MAPK signaling pathways." (PMID 39858497, 2025). "However, T0901317 15 a sulphonamide compound exerts its pyroptotic effects on non-small cell lung cancer (NSCLC) tumor cells by activating caspase-1 and NLRP3." (PMID 39316325, 2025).
non-small cell lung carcinoma (continued). "In addition to the NLRP3 inflammasome, the AIM2 inflammasome was reported to present high expression levels in non-small cell lung cancer cells (NSCLCs) and to exert tumor-promoting ability both in vivo and in vitro." (PMID 38016064, 2023). "NLRP3 inflammasome-mediated pyroptosis promotes the progression of lung adenocarcinoma but inhibits the progression of non-small-cell lung cancer, while GSDMD-mediated pyroptosis promotes the progression of non-small-cell lung cancer." (PMID 35246158, 2022). "The induction of caspase-1-mediated pyroptosis in non-small cell lung cancer (NSCLC) by Polyphyllin VI (PPVI) was seen via the signaling axis of ROS, nuclear factor kappa B (NF-κB), nod-like receptor family pyrin domain containing 3 (NLRP3), and gasdermin D (GSDMD)." (PMID 37998025, 2023).